MMP12 (matrix metallopeptidase 12)
Diseases named in the same sentence as MMP12 in open-access papers (continued):
Sharing a sentence is not in itself a finding about the gene and the disease.
ovarian carcinoma (8 papers, 2017 to 2025). A malignant neoplasm originating from the surface ovarian epithelium. "The MMP12 82A/G polymorphism has been associated with increased susceptibility to ovarian cancer, and MMP13 in ascitic fluids of ovarian cancer patients has been identified as a potential marker for disease risk and survival outcomes." (PMID 40558552, 2025). "The overexpression of MMP12 is associated with poor prognosis and increased risk of recurrence in many types of cancer, including lung, colon, breast, and ovarian cancers." (PMID 38560573, 2024). "In contrast, researchers have reported that overexpression and functional polymorphism of MMP-12 is correlated with the occurrence and progression of colon cancer and ovarian cancer." (PMID 37513440, 2023). "The signaling pathway involving MAPK/AP-1/MMP12 is involved in IL-1β-regulated ovarian cancer progression." (PMID 40244135, 2025). "Studies have documented that MMP-12 has antitumor activity against specific types of cancer, such as ovarian cancer and colorectal cancer." (PMID 37513440, 2023). "Ovarian cancer patients with high levels of MMP12 mRNA have better overall survival." (PMID 40244135, 2025). "In addition, MMP12 has been regarded as a potential prognostic biomarker for ovarian cancer and gallbladder cancer." (PMID 34552928, 2021). "MMP-12 82 A/G polymorphism increases the susceptibility to ovarian cancer despite not being significantly associated with overall cancer risk." (PMID 28538838, 2017). "The systematic review on 12 polymorphisms suggested that MMP2 C-735T, MMP7 A-181G, MMP8 rs11225395, MMP9 rs6094237, MMP12 rs2276109, MMP20 rs2292730, MMP20 rs12278250, MMP20 rs9787933 might have a potential effect on ovarian cancer risk." (PMID 28957437, 2017). "Furthermore, a meta-analysis that aimed to study the association between MMP-12 polymorphism and cancer concluded that the G allele of the MMP-12 82 A/G polymorphism may significantly increase the risk of epithelial ovarian cancer." (PMID 37513440, 2023). "It has been suggested that MMP-12 82 A/G polymorphism may increase the susceptibility of ovarian cancer despite not being significantly associated with overall cancer risk." (PMID 28538838, 2017). "Progression-free survival depended on the expression level of MMP12, MMP13, PYCR1 and GPx1 in patients with ovarian cancer." (PMID 38397798, 2024). "Most of the tested metalloproteinases upregulated mRNA expression in both FIGO I/II and FIGO III/IV stages of ovarian cancer (MMP1, MMP13, MMP2, MMP9, MMP10, MMP7, MMP12 and MMP14) indicating profound modifications of the extracellular matrix." (PMID 38397798, 2024). "Moreover, only the expressions of MMP7, MMP12, TIMP3, CAT and Nrf2 were affected by the clinical stage of ovarian cancer." (PMID 38397798, 2024). "However, the relationship between IL-1β, JNK, and MMP12 in ovarian cancer has not been reported." (PMID 40244135, 2025). "Eight polymorphisms (MMP2 C-735T, MMP7 A-181G, MMP8 rs11225395, MMP9 rs6094237, MMP12 rs2276109, MMP20 rs2292730, MMP20 rs12278250, MMP20 rs9787933) were reported associated with ovarian cancer risk, while other polymorphisms could not be associated with ovarian cancer risk." (PMID 28957437, 2017).
viral infection (8 papers, 2017 to 2026). "After viral infection of cells, macrophages secrete MMP-12, which is taken up by epithelial cells, in which it acts as a transcriptional activator of IκBα expression, which in turn is required for efficient release of IFNα to fight viral infection." (PMID 41266616, 2026). "For example, macrophages can release MMP-12 during a viral infection, which can also enter infected cells and be translocated to the nucleus, presumably through endocytosis and lipid-dependent trafficking." (PMID 33352765, 2020). "Collectively, inhibition of extracellular MMP-12 or increasing its nuclear localization (or activity) highlights a potential basis on which the development of a therapeutic strategy against viral infection could be implemented." (PMID 33352765, 2020). "Additionally, MMPs may have opposing roles depending on the stage of disease or infection (e.g., MMP12 is protective early in viral infection but detrimental later)." (PMID 41226358, 2025). "Viral infections may activate the expression of MMP3 in astrocytes and MMP12 in CNS cells and infiltrating cells." (PMID 38803919, 2024). "However, in the absence of MMP-12 expression (in a knockout mouse model), in mice infected with Coxsackie B type B2 virus, unsecreted IFN-α protein remained within pancreatic, heart, and hepatocyte cells and the mice succumbed to the lethal effects of viral infection." (PMID 33352765, 2020).
diabetes (7 papers, 2015 to 2022). "Mmp12, part of the inflammatory matrix metalloproteinase family, was up‐regulated in the SCN 143‐fold during diabetes but unaffected by pioglitazone treatment, supporting our previous study which demonstrated Mmp12 up‐regulation in the SCN of leptin‐deficient BTBR ob/ob mice." (PMID 28272773, 2017). "Significantly lower levels of elastin, collagen and MMP-12 were found in patients with diabetes as compared with non- diabetics." (PMID 25803692, 2015). "The increased risk remained significant for KIM-1, UPAR, MMP12, cathepsin L1, TNFR2, and CX3CL1 after adjustments for cardiovascular risk factors (i.e., diabetes, systolic blood pressure, blood lipids, use of blood pressure or lipid-lowering medications and waist circumference)." (PMID 31114450, 2019).
Granuloma (7 papers, 2014 to 2025). A compact, organized collection of mature mononuclear phagocytes, which may be but is not necessarily accompanied by accessory features such as necrosis. "Further studies were performed in Mmp12 KO mice to explore the mechanism associated with granuloma resolution." (PMID 34681679, 2021). "MMP12 is a macrophage elastase that degrades extracellular matrix fibres, in particular elastin, and that is involved with granuloma formation; MMP12 was one of the top five upregulated genes in typical GCA (available at Rheumatology online)." (PMID 39837478, 2025). "As previously reported, granulomas resolved at 60 days in Mmp12 KO mice while granuloma formation persisted in C57Bl/6 wild-type mice." (PMID 34681679, 2021). "Between 10 and 60 days, the increased IL-13 resulted in a M2a macrophage phenotype when granulomas were resolving in MWCNT-instilled Mmp12 KO mice." (PMID 34681679, 2021). "Studies with MMP12 KO mice revealed similar acute reactions to those in wild-type but at chronic time points where wild-type maintained granulomatous disease, resolution occurred with MMP12 KO mice suggesting MMP12 is necessary for granuloma progression." (PMID 33918196, 2021). "In the MWCNT-instilled Mmp12 KO, increased PPARγ expression coincided with this granuloma resolution." (PMID 34681679, 2021). "Previously, we reported that oropharyngeal instillation of multiwall carbon nanotubes (MWCNT) into C57Bl/6 mice induced sarcoid-like granulomas and upregulation of MMP12." (PMID 34681679, 2021). "Correspondingly, ApoE expression is increased in MWCNT-instilled Mmp12 KO mice at 60 days, when granulomas are resolving." (PMID 34681679, 2021). "With MMP12 upregulation (C57/Bl6), persistent PPARγ decrease and IFNγ increase results in granuloma persistence." (PMID 33072094, 2020). "To explore MMP12 involvement in granuloma development, we examined the time course of Mmp12 expression." (PMID 33072094, 2020). "Overall, our results strongly implicate MMP12 as a key factor in granuloma persistence and as a possible therapeutic target in chronic pulmonary sarcoidosis." (PMID 33072094, 2020). "Elevation of CCL2 in BAL cells was unexpected in Mmp12 KO mice at 60 days after MWCNT instillation when granulomas had resolved." (PMID 33072094, 2020). "The striking reduction of granuloma formation at day 60 in Mmp12 KO mice suggests that MMP12 is required to maintain chronic granuloma pathophysiology." (PMID 33072094, 2020). "The current findings in the murine MWCNT granuloma model highlight the importance of MMP12 in granuloma pathophysiology and complement findings in sarcoidosis." (PMID 33072094, 2020). "In contrast, by 20 days after MWCNT instillation, granulomas in Mmp12 KO mice appeared to be resolving and by 60 days were smaller and less well-formed." (PMID 33072094, 2020). "We hypothesized that at 60 days, high levels of ApoE in Mmp12 KO mice instilled with MWCNT might coincide with granuloma resolution." (PMID 34681679, 2021). "However, in a time course comparison, it was observed that while granulomas persist through 60 days in C57Bl/6 mice, granulomas in Mmp12 KO mice were resolving." (PMID 34681679, 2021). "Based on these observations, we hypothesized that ApoE might also play a role in transforming the Mmp12 KO macrophage phenotype into a form responsible for granuloma resolution." (PMID 34681679, 2021). "We hypothesized that as granulomas in Mmp12 KO mice were diminished at 60 days, mediastinal lymphadenopathy would also be attenuated in these mice." (PMID 33072094, 2020). "Interestingly, a role of MMP12 in granuloma resolution is also suggested by increases in both macrophage influx and CCL2." (PMID 33072094, 2020). "Here we hypothesized that MMP12 is important to acute and late phases of granuloma pathogenesis." (PMID 33072094, 2020).
Granuloma (continued). "Similar to other forms of sarcoidosis, the expression of RUNX1, MMP9, MMP12, CCR5, ITGAX, CD44, and human leukocyte antigens (HLA) is also seen in the granuloma of CS." (PMID 40521183, 2025). "Even though, Mmp12 KO mice instilled with MWCNT are intrinsically an M2 phenotype, our data suggest that the necessary M2c to M2a shift for granuloma resolution might be induced by IL-13." (PMID 34681679, 2021). "Whereas in the absence of MMP12 (Mmp12 KO), PPARγ increases and IFNγ decreases, resulting in granuloma resolution." (PMID 33072094, 2020).
melanoma (7 papers, 2014 to 2025). A malignant, usually aggressive tumor composed of atypical, neoplastic melanocytes. "Among the genes involved in tissue remodelling, a significant difference between the two culture conditions was observed only for MMP-12, a key enzyme implicated in melanoma progression." (PMID 40869222, 2025). "The presence of MMP-12 is associated with melanoma cell invasion, lymph node and tumor metastasis, as well as prognosis in melanoma patients." (PMID 39582871, 2024). "Importantly, ZDHHC13 also reshapes the tumor immune microenvironment by suppressing lysophosphatidylcholine (LPC) synthesis in melanoma cells, leading to inhibition of M2-like tumor-associated macrophages that we show degrade E-cadherin via MMP12 expression." (PMID 41321310, 2025). "Afterwards, we transiently transfected A375 melanoma cells with a MMP12 cDNA containing vector (A375-MMP12) and analyzed their biological characteristics with respect to empty vector transfected cells (A375-EV)." (PMID 25003596, 2014). "To further verificate the role of MMP-12 in inhibiting tumor invasion, we transiently transfected A375 melanoma with MMP12 expression vector and demonstrated that its consequent upregulation impaired uPAR-dependent melanoma cell invasion." (PMID 25003596, 2014). "Our results show that administration of autologous 111In-oxine labelled MMP12-lentiviral modified ECFCs can provide a theranostic appoach to human melanoma progression and metastasis." (PMID 25003596, 2014). "The i.v. injection of radiolabelled MMP12-ECFCs can thus provide a new theranostic approach to control melanoma progression and metastasis." (PMID 25003596, 2014). "While confirming the data obtained in vitro these results also indicate that the release of MMP12 by engineered ECFCs recruited in the tumor mass impairs tumor growth and metastasis mainly by inhibiting uPAR-dependent angiogenesis and spread of melanoma cells." (PMID 25003596, 2014). "Moreover, elevated SMPD2 expression was positively correlated with increased M2 macrophage infiltration, higher MMP12 expression, and poorer survival outcomes in melanoma patients, further validating and reinforcing the clinical relevance of our findings." (PMID 41321310, 2025). "Importantly, our data show that concurrent activation of both downstream arms of ZDHHC13 signaling — enhanced CTNND1 palmitoylation and suppression of macrophage-derived MMP12 — produces the most robust inhibition of melanoma metastasis." (PMID 41321310, 2025). "In this study we suggest, for the first time, the employment of MMP12 as biological drug in the anti-tumoral cell-based therapy in order to impair tumor angiogenesis and tumor invasion of melanoma and of all those tumor which heavily depend on uPAR to perform invasion." (PMID 25003596, 2014). "The possibility to exploit tumor homing and activity of autologous MMP12-engineered ECFCs represents a novel way to combat melanoma by a “personalized therapy”, without rejection risk." (PMID 25003596, 2014). "We hypothesized that delivery of ECFCs engineered to express MMP12 into human melanomas transplanted in nude mice could release such metalloproteinase into tumor mass thereby controlling melanoma progression." (PMID 25003596, 2014). "Among the genes downregulated by melanoma-derived SPN, MMP-1, MMP-3, and MMP-12 showed similar expression patterns in both NHFs and CAFs." (PMID 40869222, 2025). "By targeting MMP9, MMP12, MMP14, and MMP16, it is conceivable that Estradiol and Calcitriol could disrupt critical pathways involved in melanoma progression, offering a novel and potentially effective approach for combating this aggressive form of skin cancer." (PMID 39493455, 2024). "Recent studies based on mRNA and protein expression show that several MMPs, namely MMP-9, MMP-12 MMP-2, MMP-14, and MMP-19, play a role in melanoma aggressiveness and consequently may represent useful prognostic biomarkers." (PMID 30591049, 2018).
non-small cell lung carcinoma (7 papers, 2013 to 2025). A group of at least three distinct histological types of lung cancer, including non-small cell squamous cell carcinoma, adenocarcinoma, and large cell carcinoma. "Consistent with our hypothesis, elevated expression of MMP12 was previously associated with metastatic disease in non-small cell lung cancer and head and neck squamous cell carcinoma." (PMID 24885469, 2014).
osteoarthritis (7 papers, 2006 to 2024). A noninflammatory degenerative joint disease occurring chiefly in older persons, characterized by degeneration of the articular cartilage, hypertrophy of bone at the margins and changes in the synovial membrane. "These prostaglandins, PGE2 and PGF2α, then induced expression of an osteoarthritis-associated enzyme called MMP-12 that destroys the supporting structure that surrounds cartilage cells." (PMID 30510777, 2018). "The researchers, working both in human cells and in mouse models, further delineated several intermediate signaling molecules in the pathway linking shear stress with MMP-12 activation, thereby revealing several new potential drug targets for combating osteoarthritis in patients." (PMID 30510777, 2018). "Previous report has shown that increased MMP-1, MMP-3, MMP-9, MMP-12, and MMP-13, VEGF-A, and COL10A1, triggered by hypoxia-inducible factor (HIF)-2, play a vital role during osteoarthritis development." (PMID 31766662, 2019). "The genes enriched in the osteoarthritis pathway revealed by IPA of the DEGs in the palovarotene-treated chondrocytes included various matrix catabolic genes (Adamts4, Adamts5, Mmp9, Mmp10, Mmp12, and Mmp13) and cell death-related genes (Casp1, Casp3, and Casp6)." (PMID 39062860, 2024).
periodontitis (7 papers, 2016 to 2024). An acute or chronic inflammatory process that affects the tissues that surround and support the teeth. "Studies have implicated the association of MMP12 expression with the pathogenesis of several representative oral diseases, including periodontitis, TMD, OSCC, OTM, and bone remodelling." (PMID 36902078, 2023). "Similar to the functions of other MMPs in the pathogenesis of chronic periodontitis, the production of MMP12 can cause damage to periodontal tissue." (PMID 36902078, 2023). "However, the relationship between MMP12 and the tissue degradation associated with chronic periodontitis remains uncertain." (PMID 36902078, 2023). "MMP12 is one of the critical proteases, with a range of physiological and pathological activities, which has been linked to pro-inflammatory and tissue-remodelling pathways that underpin oral illnesses and tissue remodelling, such as periodontitis, TMD, OSCC, and OTM, as well as bone remodelling." (PMID 36902078, 2023). "Nonetheless, it remains unknown whether MMP12 can directly destroy periodontal pathogens during the early stages of periodontal diseases, as dysbiosis is closely associated with the development of periodontitis." (PMID 36902078, 2023). "One study reported that MMP-12 mRNA and protein are elevated in the gingival tissue of periodontitis patients and expressed by cells of monocyte origin." (PMID 39101637, 2024). "The existence of MMP12-producing monocytes and decreased tropoelastin levels in periodontitis patients’ inflamed gingival tissue was determined as a novel route contributing to periodontal aetiology." (PMID 36902078, 2023). "It was demonstrated to reduce MMP12 activity in vitro and improves the clinical outcome of periodontitis treatment." (PMID 36902078, 2023). "Consistent with this work, the only statistically significant variation in MMP12 levels 24 h after activation of periodontitis teeth undergoing orthodontic therapy was observed." (PMID 36902078, 2023). "To date, this review represents the latest comprehensive overview of MMP12 in various oral diseases, such as periodontitis, temporomandibular joint dysfunction (TMD), orthodontic tooth movement (OTM), and oral squamous cell carcinoma (OSCC)." (PMID 36902078, 2023). "A recent bioinformatic study identified that MMP12 is one of the hub genes that mediate the inflammatory process in periodontitis through the IL-17 signalling pathway." (PMID 36902078, 2023). "In periodontitis patients, MMP12 production and other inflammatory mediators were attenuated in response to the blocking of CSF-1 receptor (CSF-1R) in the inflamed gingiva and circulating monocytes." (PMID 36902078, 2023). "MMP-12 expression found elevated in patients with chronic periodontitis with identification of CD68+ CD14+ CD64+ cells." (PMID 33892690, 2021). "MMP-12 −357 Asn/Ser as well as MMP-13 −77 A/G and 11A/12A SNPs, located on 11q22.2-q22.3 chromosomes, has been evaluated with the periodontitis risk in a limited number of studies." (PMID 27194818, 2016). "A few articles have reported the relation of MMP-12 −357 Asn/Ser as well as MMP-13 −77 A/G and 11A/12A SNPs to periodontitis risk in Caucasian population." (PMID 27194818, 2016). "As MMP-12 exhibits several important functions in tissue remodeling, immune regulation, and wound healing, its role in periodontitis should be further explored." (PMID 39101637, 2024). "For instance, Aggregatibacter actinomycetemcomitans promoted the expression of CSF-2 in the gingival epithelium cells, which may drive the production of MMP12 in periodontitis." (PMID 36902078, 2023). "Moreover, a recent study discovered that MMP12 was highly overexpressed in chronic periodontitis tissue." (PMID 36902078, 2023). "Furthermore, the MMP12 expression level in the gingival crevicular fluid (GCF) of patients with aggressive periodontitis was reduced after periodontal treatment." (PMID 36902078, 2023).